BMPR2 (bone morphogenetic protein receptor type 2)
Diseases named in the same sentence as BMPR2 in open-access papers (continued):
Sharing a sentence is not in itself a finding about the gene and the disease.
osteosarcoma (continued). "The silencing of BMPR2 inhibits invasion and metastasis by the RhoA/ROCK/LIMK pathway, and that also indicates a potential therapeutic target for osteosarcoma." (PMID 28938584, 2017). "Here, we found that the expression of MMP-2 was diminished after the BMPR2-depleted in 143B cells, so we suggest that MMP2 were involved in the BMPR2-induced MET in osteosarcoma cells." (PMID 28938584, 2017). "As BMPR2 silencing promoted MET and restrained in vitro migration and invasion of osteosarcoma cells, we further investigated whether BMPR2-depletion will affect in vivo growth and metastasis of tumor." (PMID 28938584, 2017). "Although we provide a link between BMPR2 and MET in osteosarcoma, the mechanism of whether BMPR2 regulates MET directly or indirectly needs further study." (PMID 28938584, 2017). "The expression levels of BBRN supercomplex (RGMb, BMPR2, and Neo1) in the primary and metastatic osteosarcoma tumors were evaluated by IHC, and the results indicated BBRN supercomplex expression was increased in lung metastases compared with primary osteosarcoma." (PMID 30886151, 2019). "Taken together, our study revealed that BMPR2 functions as a prometastatic oncogene in vitro and in vivo with the activation of the RhoA-ROCK-LIMK2 pathway and may represent a potential therapeutic target for osteosarcoma." (PMID 28938584, 2017).
chondrosarcoma (7 papers, 2014 to 2025). A malignant cartilaginous matrix-producing mesenchymal neoplasm arising from the bone and soft tissue. "Our results show that higher BMPR2 expression is associated with higher pathological stage and poorer survival, and also illustrate the antineoplastic effects of siBMPR2 on chondrosarcoma cells in vitro and in vivo." (PMID 25501832, 2014). "Their results suggest that BMPR2 plays a vital role in the development of chondrosarcoma and can function as a valuable prognostic indicator for this type of cancer." (PMID 40136410, 2025). "Inhibition of BMPR2 induces apoptosis and autophagy in human chondrosarcoma by destabilization of XIAP." (PMID 34903128, 2021). "In human chondrosarcoma cells, BMPR2 inhibited apoptosis and autophagy through destabilization of XIAP." (PMID 31889906, 2019). "The expression of BMPR2 in chondrosarcoma also directly correlates to a significantly reduced relapse-free survival." (PMID 30149506, 2018). "Knockout of BMPR2 in chondrosarcoma with siRNA destabilized XIAP, increased tumor apoptosis, suppressed tumor growth, and increased autophagy." (PMID 30149506, 2018). "In the current study, we investigated the prognostic value of BMPR2 expression in 78 chondrosarcomas patient, and the effects of BMPR2 small interfering RNA (siBMPR2) on human chondrosarcoma cell lines HCS-2/8 and SW1353." (PMID 25501832, 2014). "Taken together, these results suggest that knockdown of BMPR2 reduced the level of XIAP through a Smad-independent pathway in chondrosarcoma cells." (PMID 25501832, 2014). "In conclusion, results from this study demonstrate that BMPR2 has a crucial role in promoting tumorigenesis and growth of chondrosarcoma." (PMID 25501832, 2014). "Collectively, these results elucidate that suppression of BMPR2 using siRNA induces autophagy of chondrosarcoma cells." (PMID 25501832, 2014). "The correlation between BMPR2 expression and the clinicopathological parameters of chondrosarcoma patients was analyzed." (PMID 25501832, 2014). "Results from this study have the direct potential to develop BMPR2 as an important biomarker for prognosis of chondrosarcoma and a therapeutic target for chondrosarcoma, especially for those with BMPR2 overexpression." (PMID 25501832, 2014). "It has been demonstrated that more prevalent expression of bone morphogenetic protein receptor 2 (BMPR2) has been detected in dedifferentiated chondrosarcomas than conventional chondrosarcomas." (PMID 25501832, 2014). "Small interfering RNA (siRNA) was used to knock down BMPR2 to investigate the effect of BMPR2 on maintenance of cell viability in chondrosarcoma cell lines." (PMID 25501832, 2014). "Western blot analyses were performed on 12 samples taken from the normal articular cartilage and chondrosarcoma tissues to investigate the expression of BMPR2 and clinical importance of BMPR2 in chondrosarcomas, respectively." (PMID 25501832, 2014). "BMPR2 expression was detected as low-grade chondrosarcoma in 7 of 25 patients (grade I), high-grade chondrosarcomas in 14 out of 30 patients (grade I+II) and dedifferentiated chondrosarcomas in 18 of 23 patients." (PMID 25501832, 2014). "Inhibiting BMPR2 could potentially provide a beneficial therapeutic approach for the treatment of chondrosarcoma." (PMID 40136410, 2025). "BMPR2 in chondrosarcoma stabilizes XIAP, leading to apoptosis resistance." (PMID 30149506, 2018).
chondrosarcoma (continued). "The prognosis analysis showed that the rate of survival in chondrosarcoma patients was poor in case of higher expression levels of BMPR2, indicating that BMPR2 could be a prognostic marker for poor prognosis of chondrosarcomas." (PMID 25501832, 2014). "Results from the current study demonstrated that overexpression of BMPR2 may lead to chondrosarcoma tumorigenesis." (PMID 25501832, 2014). "In addition, by using Kaplan–Meier survival analysis (P=0.030), it was found that expression levels of BMPR2 were related with disease-free survival of chondrosarcoma patients." (PMID 25501832, 2014). "Here, we find that BMPR2 inhibition induces apoptosis and autophagy of chondrosarcoma." (PMID 25501832, 2014). "Knockdown of BMPR2 by small interfering RNA results in growth inhibition in chondrosarcoma cells." (PMID 25501832, 2014). "Taken together, our results suggest that BMPR2 has a significant role in the tumorigenesis of chondrosarcoma, and could be an important prognostic marker for chondrosarcoma." (PMID 25501832, 2014). "We found that BMPR2 expression was correlated with the clinicopathological features of chondrosarcomas, and could predict the treatment outcome." (PMID 25501832, 2014). "Although BMPR2 has been studied in many types of cancers, the association between BMPR2 and prognosis of chondrosarcoma has not been reported." (PMID 25501832, 2014). "In addition, these results also demonstrate that inhibiting BMPR2 triggers autophagy in chondrosarcoma, whereas inhibition of autophagy promotes apoptosis, suggesting that autophagy has a cytoprotective role for chondrosarcoma cells in the context of siBMPR2-induced apoptotic cell death." (PMID 25501832, 2014). "Furthermore, whether BMPR2 expression levels might serve as a biomarker for treatment outcome was evaluated, for that a cohort of 78 chondrosarcoma patients was included in the current study." (PMID 25501832, 2014). "Therefore, repressing BMPR2 inhibited chondrosarcoma cell growth." (PMID 25501832, 2014). "Inhibition of autophagy induced by BMPR2 small interfering RNA (siBMPR2) sensitized chondrosarcoma cells to siBMPR2-induced apoptotic cell death, suggesting that autophagy has a protective role for chondrosarcoma cells in context of siBMPR2-induced apoptotic cell death." (PMID 25501832, 2014). "BMPR2 inhibition could eventually provide a promising therapy for chondrosarcoma treatment." (PMID 25501832, 2014). "Western blot analysis showed that BMPR2 was expressed in chondrosarcomas but not in the normal articular cartilage tissues." (PMID 25501832, 2014). "Similarly, we found that downregulation of both BMPR2 and XIAP led to obviously increased cleaved PARP and caspase-3, indicating that inhibition of BMPR2 or XIAP induced apoptosis of chondrosarcoma cells." (PMID 25501832, 2014). "As BMPR2 is expressed in chondrosarcoma but not in normal articular cartilage tissues, it was interesting to research whether inhibition of BMPR2 would kill human chondrosarcoma cell lines (HCS-2/8 and SW1353)." (PMID 25501832, 2014).
Insulin resistance (7 papers, 2017 to 2023). Increased resistance towards insulin, that is, diminished effectiveness of insulin in reducing blood glucose levels. "A causal relationship between insulin resistance and PAH has been suggested based rodent models with BMPR2 mutations developing insulin resistance early in their disease process." (PMID 36982922, 2023). "Metabolomic analysis demonstrated that BMPR2 mutations were associated with a wide range of metabolic abnormalities, including oxidative injury and insulin resistance in human pulmonary ECs." (PMID 32028950, 2020). "Interestingly, insulin resistance is also present in experimental PH of BMPR2 mutated mice, the predominant cause of hereditary PAH in humans." (PMID 28446163, 2017). "The link between BMPR2 dysfunction and insulin resistance is thought to bemediated by PPARγ, a downstream target of BMPR2." (PMID 32999709, 2020).
ovarian carcinoma (7 papers, 2010 to 2024). A malignant neoplasm originating from the surface ovarian epithelium. "On the other hand, BMPR2 is expressed in ovarian cancer, with levels correlating to improved survival." (PMID 30149506, 2018). "However, BMPR2 enhances ovarian cancer progression, indicating its oncogenic role of BMPR2 in ovarian cancer." (PMID 38538669, 2024). "Finally, study of ovarian cancer cell lines indicates BMP-15-mediated BMPR2 signaling regulates steroidogenesis by decreasing production of progesterone in response to follicle stimulating hormone (FSH) stimulation." (PMID 30149506, 2018). "BMP9 can act through BMPR2 to promote ovarian cancer proliferation." (PMID 30149506, 2018). "Low BMPR2 expression and down-regulated UNC5C are associated with epithelial ovarian cancer." (PMID 25591662, 2015). "Furthermore, high BMPR2 mRNA expression correlates with poor prognosis in ovarian cancer." (PMID 34360647, 2021).
Right ventricular hypertrophy (7 papers, 2012 to 2025). In this case the right ventricle is more muscular than normal, causing a characteristic boot-shaped (coeur-en-sabot) appearance as seen on anterior- posterior chest x-rays. "In vivo R428 aggravated right ventricular hypertrophy and dysfunction, abrogated BMPR2 signaling, elevated pulmonary endothelial cell apoptosis and loss." (PMID 34429509, 2021). "In conclusion, ZDF rats show increased pulmonary arterial pressure, right ventricular hypertrophy, pulmonary arterial medial thickening and downregulated lung Bmpr2 despite leptin resistance." (PMID 30689673, 2019). "It is interesting to note that mutations in the BMPR2 gene, which encodes the major type II receptor for the large family of BMPs, is the most common genetic cause of PAH, a disease characterized by the extensive remodeling of pulmonary arteries, right ventricular hypertrophy and heart failure." (PMID 26631724, 2016). "Another study utilizing Bmpr2+/− mice, found that a combination of hypoxia and chronic serotonin infusion increased RVSP, right ventricular hypertrophy, and pulmonary remodeling." (PMID 22427841, 2012). "Taken together, in the present study, our results confirmed that MSC‐EXO could significantly suppress the vascular remodelling and right ventricular hypertrophy induced by MCT, which through regulation of Wnt5a and/or BMPR2 signalling pathway and then inhibition of EndMT process." (PMID 33090702, 2020).
congenital heart disease (6 papers, 2018 to 2024). "Genetic testing showed that 5 out of 19 idiopathic and Congenital Heart Disease PAH patients had Bone Morphogenetic Protein Receptor 2 (BMPR2) mutations at 25% prevalence, with 2 of these patients exhibiting a novel mutation." (PMID 29843651, 2018). "Of note, beyond heterozygous BMPR2 germ line mutations in familial PAH, both idiopathic PAH and associated PAH (APAH) due to interstitial lung disease, connective tissue disease, or congenital heart disease are associated with lower levels of BMPR2 expression and signaling." (PMID 30149506, 2018). "Indeed, ID proteins are among the most highly regulated downstream targets of BMP/Smad signaling, and their importance was recently reported, as the loss of ID1 and ID3 expression associated with BMPR2 mutations contributed to cardiomyocyte dysfunction in patients with congenital heart disease." (PMID 37298503, 2023). "Gremlin-1 was found to play vital roles in PAH associated with congenital heart disease (systemic-to-pulmonary shunts), which does not typically arise from BMPR2 mutation; in this case, gremlin-1 could help to explain reduced BMPRII–SMAD1/5/8 pathway activity in the presence of intact BMPR263." (PMID 35551212, 2022).
prostate carcinoma (6 papers, 2010 to 2020). A carcinoma that arises from epithelial cells of the prostate gland. "The suppressive effect on cell proliferation by BMP-7 depends on the BMP receptor 2 (BMPR2), and BMPR2 expression inversely correlates with bone metastases in prostate cancer patients." (PMID 27819283, 2016). "In prostate cancer BMPR1A and especially BMPR2 downregulation has been correlated with disease progression and activity of BMPR2 has been shown to function in a proliferation suppressive way." (PMID 22277058, 2012). "Constitutively-active ALK6QD receptor expression decreases the proliferation of human prostate cancer cells as well as their ability to form tumours in nude mice, whereas blocking BMP signalling by expression of dominant-negative BMPR2 enhances prostate cancer tumorigenicity." (PMID 20187934, 2010).
atherosclerosis (5 papers, 2017 to 2024). A disease characterized by the build-up of fatty material and calcium deposition in the arterial wall resulting in partial or complete occlusion of the arterial lumen. "BMP4 accelerate the progression of atherosclerosis by induced macrophage foam cell formation through BMPR-2/Smad1/5/8 signaling." (PMID 31064817, 2019). "It well-known that the expression of BMPR-2, the receptor for classic osteogenic ligands BMP-2 and BMP-4, is decreased in patients with advanced coronary atherosclerosis and it is protective against atherosclerosis in animal models, suggesting a context-specific role of BMPR-2-mediated signalling." (PMID 39768183, 2024). "Furthermore, endothelial deletion of Bmpr2 in mice enhances the development of atherosclerosis, suggesting an atheroprotective protective role for BMPR-II." (PMID 28646109, 2017).
Hypertension (5 papers, 2006 to 2022). The presence of chronic increased pressure in the systemic arterial system. "Common gene mutation sites were analyzed to investigate the the association between single nucleotide polymorphisms (SNPs) of the BMPR2, ACVRL1, and SMAD9 genes with hypertension risk." (PMID 30617053, 2019). "We found that genes related to hypertension—such as ACE, ANG, CAD, BMPR2, and other genes—were also significantly expressed in ascending aortic dissection tissue reported in the literature." (PMID 34262602, 2021). "The drugs used in this study, which target the BMPR2 pathway and lead to T cell-mediated killing of HCMV latently infected cells, could have potential roles in the treatment of hypertension but also HCMV latency/reactivation in vivo." (PMID 34061599, 2021). "In summary, it is speculated that the BMPR2 gene can mediate the inflammatory response and maintain normal structure of lung tissue, but whether the BMPR2 gene is involved in the pathogenesis of hypertension is still unclear." (PMID 30617053, 2019).
liver cancer (5 papers, 2013 to 2024). An epithelial or non-epithelial malignant neoplasm that arises from the liver. "In liver cancer, OIP5 knockdown upregulates BMPR2 expression to inhibit the progression of liver cancer, suggesting an anticancer role for BMPR2 in liver cancer." (PMID 38538669, 2024).
myeloma (5 papers, 2015 to 2024). "The role of BMPR2 as an inhibitor of Activin-SMAD1/5/8 signaling was recently shown in myeloma cells." (PMID 31826007, 2019). "Interestingly, it was suggested that BMPRII inhibits activin signalling via ALK2 because knocking down BMPR2 by siRNA lead to enhanced ActA-phospho-SMAD1/5 signalling via ALK2 in multiple myeloma cells." (PMID 38716930, 2024). "Using myeloma cell lines as a model system, we show that activin A antagonizes BMP-6 or BMP-9-signaling through ACVR2A/ACVR2B/ALK2, but not BMP-2 or BMP-4-signaling through BMPR2/ALK3 or BMPR2/ALK6." (PMID 26047946, 2015).
pulmonary veno-occlusive disease (5 papers, 2016 to 2022). "Three African American and 16 Caucasian patients, including 1 with pulmonary veno-occlusive disease and 1 with pulmonary capillary hemangiomatosis, had mutations in the bone morphogenetic protein receptor type 2 (BMPR2), Caveolin 1 (CAV1) or EIF2AK4 gene." (PMID 27224443, 2016). "However, variants in BMPR2 have also been reported in patients with histologically proven pulmonary veno-occlusive disease (PVOD) and pulmonary capillary haemangiomatosis (PCH), which are rare forms of PAH under the current classification." (PMID 32471403, 2020). "PAH can be either idiopathic (iPAH, where the cause is unknown) or heritable (hPAH) due to mutations in predisposing genes (mainly in BMPR2), induced by drugs or toxins, or associated with overt features of venous/capillaries (pulmonary veno-occlusive disease, PVOD)." (PMID 36551306, 2022).
scleroderma (5 papers, 2013 to 2023). Scleroderma is a rare autoimmune connective tissue disorder characterized by abnormal hardening of the skin and, sometimes, other organs. "Patients with scleroderma may be predisposed to PAH due to BMPR2 promoter methylation and reduced BMPR2 expression." (PMID 33287230, 2020). "Methylation of the BMPR2 promoter in scleroderma patients is another relevant observation." (PMID 33287230, 2020). "A study indicates that enriched genes including MPO (myeloperoxidase), RXFP1, CXCL11, CTNND2, BMPR2, TLR3, CCR2, and CAV1 are altered expressed in scleroderma." (PMID 38137330, 2023).
systemic sclerosis (5 papers, 2014 to 2025). A chronic disorder, possibly autoimmune, marked by excessive production of collagen which results in hardening and thickening of body tissues. "TGFβ signaling is activated in familial PAH caused by mutation of BMPR2 and in syndromic PAH caused by systemic sclerosis or schistosomiasis." (PMID 27375481, 2016). "However, in PAH associated with systemic sclerosis, macrophage expression of MRC1, as is induced by BMPR2 mutation in the present study, correlates perfectly with development of PAH." (PMID 24713633, 2014). "Ultimately, PAH remains incurable and median survival is merely 7 years, a prognosis that is worse in various PAH subtypes, including systemic sclerosis (SSc)-associated PAH and in bone morphogenetic protein receptor type II (BMPR2) mutation carriers." (PMID 39941482, 2025).